EGFR (epidermal growth factor receptor)
Description:
Receptor tyrosine kinase binding ligands of the EGF family and activating several signaling cascades to convert extracellular cues into appropriate cellular responses. Known ligands include EGF, TGFA/TGF-alpha, AREG, epigen/EPGN, BTC/betacellulin, epiregulin/EREG and HBEGF/heparin-binding EGF. Ligand binding triggers receptor homo- and/or heterodimerization and autophosphorylation on key cytoplasmic residues. The phosphorylated receptor recruits adapter proteins like GRB2 which in turn activates complex downstream signaling cascades. Activates at least 4 major downstream signaling cascades including the RAS-RAF-MEK-ERK, PI3 kinase-AKT, PLCgamma-PKC and STATs modules. May also activate the NF-kappa-B signaling cascade. Also directly phosphorylates other proteins like RGS16, activating its GTPase activity and probably coupling the EGF receptor signaling to the G protein-coupled receptor signaling. Also phosphorylates MUC1 and increases its interaction with SRC and CTNNB1/beta-catenin. Positively regulates cell migration via interaction with CCDC88A/GIV which retains EGFR at the cell membrane following ligand stimulation, promoting EGFR signaling which triggers cell migration. Plays a role in enhancing learning and memory performance (By similarity). Plays a role in mammalian pain signaling (long-lasting hypersensitivity) (By similarity). Isoform 2 may act as an antagonist of EGF action. (Microbial infection) Acts as a receptor for hepatitis C virus (HCV) in hepatocytes and facilitates its cell entry. Mediates HCV entry by promoting the formation of the CD81-CLDN1 receptor complexes that are essential for HCV entry and by enhancing membrane fusion of cells expressing HCV envelope glycoproteins.
Synonyms: ERBB; ERBB1; HER1; ERRP; NISBD2; NNCIS; PIG61; mENA
Tractability: Small molecule: an approved drug acts on it; a structure with a bound ligand is known; a high-quality ligand is known; it has a high-quality binding pocket; it belongs to a druggable protein family. Antibody: an approved drug acts on it; UniProt places it where antibodies can reach, with high confidence; its Gene Ontology location is reachable by antibodies, with high confidence; UniProt predicts a signal peptide or a membrane-spanning region; the Human Protein Atlas places it where antibodies can reach. PROTAC: it is named in the literature on targeted protein degradation; UniProt records ubiquitination sites on it; ubiquitination databases record sites on it; its protein half-life has been measured; a small molecule that binds it is known. Other modalities: a drug acting on it is in phase 2 or 3 trials.
Target class: Kinase; Protein Kinase; Tyrosine protein kinase EGFR family; Enzyme; TK protein kinase group
Chemical probes: AFATINIB (high quality), AV-412 free base, BI-4732 (high quality), BI-8128 (high quality), CANERTINIB (high quality), CL-387785, Compound 56, DDC-01-163 (high quality), DDC-03-024-01 (high quality), FALNIDAMOL, ICX5600078, ICX5600079, JBJ-04-125-02 (high quality), LAPATINIB (high quality), ML102, OSI-413, PD 174265, PD004324, PD080672, PD080676, and 93 more
Safety:
Unwanted effects reported when the protein is acted on. In parentheses: how it was acted on, where the effect was seen, and who reports it.
hypertension (ClinPGx; Brennan et al. (2024): inhibition, cardiovascular)
alopecia (inhibition; source: Brennan et al. (2024))
ALT increase (inhibition; liver; source: Brennan et al. (2024))
AST increase (inhibition; liver; source: Brennan et al. (2024))
cardiomyopathy (inhibition; cardiovascular; source: Brennan et al. (2024))
decreased appetite (inhibition; source: Brennan et al. (2024))
diarrhoea (inhibition; gastrointestinal; source: Brennan et al. (2024))
epithelial inflammation (inhibition; source: Brennan et al. (2024))
Hepatotoxicity (activation; liver; source: Brennan et al. (2024))
interstitial lung disease (inhibition; respiratory; source: Brennan et al. (2024))
ocular keratitis (inhibition; ocular; source: Brennan et al. (2024))
Skin rash (inhibition; skin; source: Brennan et al. (2024))
weight loss (inhibition; source: Brennan et al. (2024))
Diarrhea (source: ClinPGx)
conjunctival hemorrhage (source: ClinPGx)
drug toxicity (source: ClinPGx)
heart disease (cardiovascular system; source: Force et al. (2011))
rash (source: ClinPGx)
Gene: Protein-coding gene on chromosome 7 (55,018,820 to 55,211,628, forward strand). Ensembl gene ENSG00000146648.
Subcellular location: Cell membrane; Endoplasmic reticulum membrane; Golgi apparatus membrane; Nucleus membrane; Endosome; Endosome membrane; Nucleus; Secreted (Isoform 2)
Subcellular location (Human Protein Atlas): Golgi apparatus; Plasma membrane; Basal body; Cell Junctions; End piece; Mid piece; Primary cilium; Principal piece; Predicted to be secreted
Pathways (Reactome):
Signal Transduction: Downregulation of ERBB2 signaling; EGFR Transactivation by Gastrin; EGFR downregulation; EGFR interacts with phospholipase C-gamma; ERBB2 Activates PTK6 Signaling; ERBB2 Regulates Cell Motility; Estrogen-dependent nuclear events downstream of ESR-membrane signaling; Extra-nuclear estrogen signaling; GAB1 signalosome; GRB2 events in EGFR signaling; GRB2 events in ERBB2 signaling; NOTCH3 Activation and Transmission of Signal to the Nucleus; PI3K events in ERBB2 signaling; PI5P, PP2A and IER3 Regulate PI3K/AKT Signaling; PIP3 activates AKT signaling; PLCG1 events in ERBB2 signaling; PTK6 promotes HIF1A stabilization; RAF/MAP kinase cascade; SHC1 events in EGFR signaling; SHC1 events in ERBB2 signaling; Signaling by EGFR; Signaling by ERBB2; Signaling by ERBB4
Disease: Constitutive Signaling by Aberrant PI3K in Cancer; Constitutive Signaling by EGFRvIII; Constitutive Signaling by Ligand-Responsive EGFR Cancer Variants; HCMV Early Events; Inhibition of Signaling by Overexpressed EGFR; Respiratory syncytial virus (RSV) attachment and entry; Signaling by ERBB2 ECD mutants; Signaling by ERBB2 KD Mutants; Signaling by ERBB2 TMD/JMD mutants
Developmental Biology: Developmental Lineage of Mammary Gland Myoepithelial Cells; Signal transduction by L1
Vesicle-mediated transport: Cargo recognition for clathrin-mediated endocytosis; Clathrin-mediated endocytosis
Gene expression (Transcription): TFAP2 (AP-2) family regulates transcription of growth factors and their receptors
Gene Ontology:
Molecular function: actin filament binding; cadherin binding; chromatin binding; enzyme binding; epidermal growth factor receptor activity; identical protein binding; kinase binding; protein binding; protein phosphatase binding; protein tyrosine kinase activator activity; protein tyrosine kinase activity; transmembrane signaling receptor activity; ubiquitin protein ligase binding; ATPase binding; double-stranded DNA binding; epidermal growth factor binding; MAP kinase kinase kinase activity; transmembrane receptor protein tyrosine kinase activity; ATP binding; kinase activity; protein kinase activity
Biological process: cell surface receptor signaling pathway; cell-cell adhesion; cellular response to estradiol stimulus; epidermal growth factor receptor signaling pathway; ERBB2-EGFR signaling pathway; negative regulation of apoptotic process; negative regulation of cardiocyte differentiation; negative regulation of macroautophagy; negative regulation of protein catabolic process; phosphatidylinositol 3-kinase/protein kinase B signal transduction; positive regulation of canonical Wnt signaling pathway; positive regulation of cell growth; positive regulation of cell migration; positive regulation of cell population proliferation; positive regulation of cGAS/STING signaling pathway; positive regulation of DNA repair; positive regulation of DNA replication; positive regulation of epithelial cell proliferation; positive regulation of ERK1 and ERK2 cascade; positive regulation of G1/S transition of mitotic cell cycle; positive regulation of MAPK cascade; positive regulation of miRNA transcription; positive regulation of peptidyl-serine phosphorylation; positive regulation of phosphatidylinositol 3-kinase/protein kinase B signal transduction; positive regulation of phosphorylation; and 18 more
Cellular component: basolateral plasma membrane; cell junction; cell surface; cytoplasm; early endosome membrane; endoplasmic reticulum membrane; endosome; endosome membrane; focal adhesion; Golgi apparatus; intracellular vesicle; membrane; membrane raft; multivesicular body, internal vesicle lumen; nucleus; perinuclear region of cytoplasm; plasma membrane; protein-containing complex; receptor complex; ruffle membrane; basal plasma membrane; clathrin-coated endocytic vesicle membrane; extracellular region; Shc-EGFR complex; endocytic vesicle; and 2 more
Genetic constraint (gnomAD): Loss-of-function variants: 58 observed, 152.06 expected, observed/expected ratio (o/e) 0.38, 90% interval 0.31 to 0.47. The upper end of that interval is the gene's LOEUF score, 0.47, which puts it in group 2 of 6, group 1 being the genes least tolerant of losing a copy. Missense variants: 1,307 observed, 1,647.5 expected, observed/expected ratio (o/e) 0.79, 90% interval 0.76 to 0.83. Synonymous variants: 613 observed, 616.74 expected, observed/expected ratio (o/e) 0.99, 90% interval 0.93 to 1.06.
Gene-disease validity (ClinGen):
ClinGen rates the evidence that EGFR causes each of these diseases.
non-small cell lung carcinoma (autosomal dominant): Definitive. A group of at least three distinct histological types of lung cancer, including non-small cell squamous cell carcinoma, adenocarcinoma, and large cell carcinoma.
Cancer hallmarks: change of cellular energetics (promotes); proliferative signalling (promotes); escaping programmed cell death (promotes); invasion and metastasis (promotes); angiogenesis (promotes); escaping immune response to cancer (promotes)
Homologues: Orthologues: chimpanzee EGFR (99% identical), macaque EGFR (99% identical), mouse Egfr (90% identical), rabbit EGFR (90% identical), dog EGFR (90% identical), rat Egfr (89% identical), guinea pig EGFR (89% identical), pig EGFR (88% identical), tropical clawed frog egfr (66% identical), zebrafish egfra (30% identical). Paralogues in human: ERBB4 (51% identical), ERBB2 (49% identical), ERBB3 (42% identical), EPHA5 (17% identical), EPHA2 (16% identical), EPHA4 (16% identical), EPHA3 (16% identical), EPHA7 (16% identical), EPHA6 (16% identical), IGF1R (16% identical), INSR (16% identical), EPHB2 (16% identical), and 41 more.
Diseases named in the same sentence as EGFR in open-access papers:
EGFR is named in the same sentence as 1,326 diseases in open-access papers, as found by Europe PMC text mining. Sharing a sentence is not in itself a finding about the gene and the disease. The quoted sentences say what the papers report.
lung cancer (7,204 papers, 1986 to 2026). A malignant neoplasm involving the lung. "Emerging evidence identifies human endogenous retrovirus-H long terminal repeat-associating protein 2 (HHLA2), a novel B7 family member, as a genotype-associated immune checkpoint enriched in EGFR-mutant lung cancer." (PMID 42266686, 2026). "Patients with non–small cell lung cancer (NSCLC) who harbor epidermal growth factor receptor (EGFR) mutations represent a unique subgroup." (PMID 41570298, 2026). "Specifically, IPHC has been shown to be an effective treatment for patients with EGFR kinase domain mutation‐positive lung cancer." (PMID 41470036, 2026). "Using EGFR mutations (L858R, G719A, Del19) in lung cancer cell lines as a model, IsoPS-DIA achieved subfemtomole sensitivity (LOQ 36-222 amol), excellent linearity across 4 orders of magnitude (R2 = 0.998-0.999), and high reproducibility (median CV ∼ 3%)." (PMID 41592227, 2026). "A total of 94 patients with confirmed epidermal growth factor receptor gene–mutated non–small cell lung cancer who developed rashes after EGFR-TKI treatment will be enrolled." (PMID 41570298, 2026). "The epidermal growth factor receptor (EGFR)‐TKI osimertinib is a preferred therapy for patients with non‐small cell lung cancer (NSCLC) driven by activating mutations in EGFR, unfortunately responses are heterogeneous." (PMID 41581122, 2026). "The method was validated for detection of the EGFR L858R mutation in patients with nonsmall cell lung cancer, yielding an excellent linear calibration curve (r = 0.9981), recovery rates of 95-110%, and a detection limit of 2.33%." (PMID 42045108, 2026). "We also show that hyperthermic chemotherapy can select specific EGFR mutation‐positive lung cancer cell lines and benefit from fumatinib‐based targeted therapy." (PMID 41470036, 2026). "Immune checkpoint blockade has revolutionized the treatment of lung cancer; however, therapeutic responses remain heterogeneous, particularly in patients harboring activating epidermal growth factor receptor (EGFR) mutations." (PMID 42266686, 2026). "Most of the patients with lung cancer and EGFR mutations who experience cutaneous adverse reactions to EGFR-TKIs do not seek treatment due to a lack of awareness of or confidence in existing treatment options." (PMID 41570298, 2026). "This technique has been successfully applied to detect activating and resistance mutations in the epidermal growth factor receptor (EGFR) gene from lung cancer ctDNA." (PMID 41602544, 2026). "Our finding elucidates the activation mechanism of this extracellular EGFR mutation and demonstrates the efficacy of afatinib in treating lung cancer or glioma patients with this variant." (PMID 41565660, 2026). "In this study, we identify an EGFR mutant (EGFR R252C) in a patient with multifocal lung cancer and glioma, in which arginine (R) 252 is mutated to cysteine (C) in the EGFR extracellular domain." (PMID 41565660, 2026). "Epidermal growth factor receptor-activating (EGFR-activating) mutations are established biomarkers of resistance to immune checkpoint blockade (ICB) in lung cancer, yet the precise molecular mechanism and effective therapeutic strategies remain elusive." (PMID 41538362, 2026). "To characterize the association between EGFR mutation and DC functions, we next constructed EGFR‐mutant human lung cancer cell lines by transfecting the EGFR exon 19del‐expressing virus into A549 or SPCA‐1 cells." (PMID 41144813, 2026). "Epidermal growth factor receptor (EGFR) mutations are prevalent in non‐small cell lung cancer (NSCLC), particularly in adenocarcinomas, and have reshaped the therapeutic landscape through the development of targeted therapies." (PMID 41144813, 2026). "Second, the effect of the bias introduced by sample selection was analyzed by estimating the mutation frequency of the most common EGFR kinase domain mutations in lung cancer with cBioPortal and DORM." (PMID 41567248, 2026).
lung cancer (continued). "Multivariate conditional logistic regression was used to explore the associations between lipid profiles, different lung cancer histological classifications and epidermal growth factor receptor mutation statuses." (PMID 39883280, 2025). "PC‐Cre transgenic mouse models can specifically induce mutations in Kras or EGFR in alveolar cells to trigger the development of lung cancer, and better simulate the microenvironment and tumor heterogeneity of human lung cancer." (PMID 40387186, 2025). "Mutations within carcinoma cells lead to quick relapse of lung cancer patients after targeted treatment, with many of these agents targeting EGFR." (PMID 40649937, 2025). "A growing body of evidence has demonstrated the prognostic and therapeutic significance of detecting these mutations in lung cancer patients, particularly EGFR mutations." (PMID 41373464, 2025). "Although lung cancers with EGFR mutation are generally less associated with smoking, this study found that an MPA size ≥ 29 mm was significantly associated with increased 18-month mortality (HR 2.74)." (PMID 40805260, 2025). "This recruitment strategy will facilitate a preliminary risk stratification based on family history of EGFR lung cancer." (PMID 40641929, 2025). "It has been demonstrated that when the C797S and T790M mutations are cis (located at the same allele), lung cancer cells are resistant to both the first- and third-generation EGFR-TKIs." (PMID 40361442, 2025). "Iressa (gefitnib), an FDA-approved EGFR inhibitor for lung cancer therapy, causes G1 cell cycle arrest and suppresses invasion by modulating p27 and MMP-2 in OSCC cells." (PMID 40027184, 2025). "Lung cancer has been the leading cause of cancer-related death for over two decades worldwide, and mutations on the epidermal growth factor receptor (EGFR) are the commonest driver genes in the Asian population." (PMID 40723259, 2025). "In the future, it will be of great interest to utilize other surface-modification ligands to target various high-risk cancers, such as Lamp2b-VEGF for liver cancer, Lamp2b-EGFR for lung cancer, Lamp2b-RVG for neuron cancer and Lamp2b-MG7 for stomach cancer." (PMID 40744997, 2025). "Analysis of previously published RNA sequencing data from a series of osimertinib tolerant EGFR mutated lung cancer cell lines revealed higher expression levels of FYN and KDM4A in the drug persisters, but not SRC." (PMID 40243589, 2025). "Spread of lung cancer to the brain and lining of the central nervous system is a devastating consequent of disease and is especially common with EGFR mutations." (PMID 40805138, 2025). "What is activity of treatment with high-dose third-generation epidermal growth factor receptor (EGFR) tyrosine kinase inhibitor in patients with untreated EGFR-variant non–small cell lung cancer (NSCLC) and brain metastases?" (PMID 40569623, 2025). "Utilizing ARMS-PCR for detecting EGFR mutations in patients with lung cancer enables rapid and precise identification of specific EGFR mutation types." (PMID 41156384, 2025). "This study focused on different types of lung cancer and their epidermal growth factor receptor (EGFR) mutation status." (PMID 39883280, 2025). "Non-small cell lung cancer (NSCLC) is the most common type of lung cancer, and about half of the patients had mutations in the epidermal growth factor receptor (EGFR) gene." (PMID 40181972, 2025). "EGFR-sensitive mutations predict robust responses to EGFR-TKIs in lung cancer, reinforcing the clinical actionability of specific genomic alterations." (PMID 40808963, 2025). "In lung cancer, EGFR mutations have been associated with favorable clinical responses to EGFR inhibitors, such as erlotinib or gefitinib." (PMID 39744583, 2025). "The IMpower150 trial demonstrated the efficacy of atezolizumab, bevacizumab, carboplatin, and paclitaxel (ABCP) therapy in epidermal growth factor receptor (EGFR)‐mutated non‐small cell lung cancer (NSCLC)." (PMID 40961974, 2025).